PRL (prolactin)
Diseases named in the same sentence as PRL in open-access papers (continued):
Sharing a sentence is not in itself a finding about the gene and the disease.
cyst (5 papers, 2010 to 2025). A sac-like closed membranous structure that may be empty or contain fluid or amorphous material. "For the other 12 patients, the mean tumor diameter before bromocriptine was 3.3 ± 1.7 cm (range: 1.5–6.8 cm), the mean cyst diameter was 1.4 ± 1.0 cm (range: 0.4–2.1 cm), and the mean PRL level was 3076.5 ± 2514.7 ng/mL (range: 275.4–8000 ng/mL)." (PMID 35741585, 2022). "After bromocriptine treatment, the mean tumor diameter was reduced to 2.8 ± 1.7 cm (range: 0.9–6.6 cm), the mean cyst diameter was reduced to 1.2 ± 0.8 cm (range: 0.3–1.8 cm), and the mean PRL level was reduced to 1496.1 ± 1614.4 ng/mL (range: 1.55–5140.78 ng/mL)." (PMID 35741585, 2022).
dry eye syndrome (5 papers, 2015 to 2024). A syndrome characterized by dryness of the cornea and conjunctiva. "The main condition related to a sex hormone (estrogen/androgen) imbalance and prolactin is Sjögren's syndrome, also known as dry eye syndrome, which is also associated with high levels of proinflammatory cytokines in the tear film and ocular surface epithelium 20-21." (PMID 26375566, 2015). "Compared with normal dry eye patients, prolactin content increased in those wearing contact lenses while the proline content decreased." (PMID 38420354, 2024). "The dry eye syndrome secondary to the direct effects on the lacrimal acinar cells of prolactin, transforming growth factor beta 1 (TGF-β1), and epidermal growth factor is found at the level of the lacrimal apparatus." (PMID 34441264, 2021). "There was an increased incidence of dry eye syndrome in pregnant women, secondary to the direct effects on the lacrimal acinar cells of prolactin, TGF beta 1, and epidermal growth factor." (PMID 34441264, 2021). "The study explored the impact of serum prolactin and testosterone levels on the clinical parameters of dry eye in pregnant women." (PMID 32908678, 2020). "Prolactin, lipocalin-1, lactoferrin, and lysozyme are decreased in tears of dry eye patients." (PMID 38420354, 2024).
endometrial tumors (5 papers, 2014 to 2022). "PRL mRNA is expressed in ovarian and endometrial tumors, and exogenous PRL induces proliferation in several ovarian and EC cell lines via the Ras pathway." (PMID 35820883, 2022). "Serum PRL levels are considerably elevated in patients with EC compared to levels in cancer-free patients, as well as PRLR, and PRL mRNA are overexpressed in endometrial tumors." (PMID 34745013, 2021). "What is more, the distinct effects of physiological factors on prolactin secretion shadow the credibility of this hormone in early diagnosis of endometrial tumors." (PMID 31035965, 2019). "Circulating levels of prolactin, a polypeptide hormone involved in numerous physiological processes including reproduction, are higher among EC patients compared to healthy controls, and increased PRLR expression has been noted for endometrial tumors compared to non-cancerous endometrial tissue." (PMID 24096698, 2014).
escherichia coli infection (5 papers, 2021 to 2025). Infection with the organism Escherichia Coli. "The KEGG pathway enrichment highlighted several significant clusters, including the prolactin signaling pathway, proteoglycans in cancer, pathogenic Escherichia coli infection, dopaminergic synapse, ERB signaling pathway, mitophagy, and necrosis." (PMID 41331739, 2025). "A previous study focused on the effects of both plants on erythropoiesis and prolactin hormone levels following S. Typhi infection and progesterone, estrogen, and prolactin hormone levels after E. coli infection." (PMID 34220146, 2021).
female infertility (5 papers, 2015 to 2025). Diminished or absent ability of a female to achieve conception. "Not only that, but serum prolactin levels may also be elevated in patients with pSS, which are widely considered to be associated with female infertility." (PMID 38769525, 2024).
Hepatitis (5 papers, 2018 to 2021). Inflammation of the liver. "Additionally, the index of ALT and AST was higher in PCOS compared with non-PCOS patients (none exhibited hepatitis or liver dysfunction), after controlling for BMI, and PRL was inversely associated with ALT." (PMID 33716958, 2021). "In our PCOS patients, the serum PRL level was within normal range and patients with hepatitis and abnormal liver function were excluded The analysis showed that PRL is negatively correlated with AST, ALT, γ –GGT, and ALP, suggesting that lower serum PRL may damage liver cells." (PMID 32477263, 2020).
hepatitis C (5 papers, 2021 to 2023). "The results demonstrated that these genes were enriched in cellular modified amino acid metabolism, ROS biosynthesis regulation, aging process, biosynthetic process, and other biological processes, and KEGG signaling pathways such as hepatitis C and prolactin signaling pathway." (PMID 36071497, 2022). "Furthermore, our enrichment analysis (GO and KEGG) revealed the significant enrichment of such genes into biological processes such as cellular modified amino acid metabolism, ROS biosynthesis regulation, and aging, and signal pathways, such as hepatitis C and prolactin signaling pathway." (PMID 36071497, 2022).
ischemia (5 papers, 2018 to 2023). A hypoperfusion of the BLOOD through an organ or tissue caused by a PATHOLOGIC CONSTRICTION or obstruction of its BLOOD VESSELS, or an absence of BLOOD CIRCULATION. "The aim of this study was to analyse the protective effect of zinc and zinc–prolactin systems as additives of preservation solutions in the prevention of nephron damage caused during ischemia." (PMID 34200394, 2021). "Serum PRL levels were not significantly different between hypoxia/ischemia cases and other causes of death." (PMID 29949606, 2018).
ischemic stroke (5 papers, 2020 to 2023). A stroke disorder caused by obstruction of blood flow to the brain, due to thrombotic (local blood clot formation) or embolic (due to a blood clot or other material traveling from another site) event. "Lastly, increased prolactin levels seem to be a risk factor for ischemic stroke and venous thromboembolism, and this association is partially related to a prolactin-induced increase in platelet activation." (PMID 37176648, 2023). "In recent years, many studies have been done on the role of thyroid hormone, growth hormone, testosterone, prolactin, oxytocin, glucocorticoid, parathyroid hormone, and dopamine in ischemic stroke, but comprehensive reviews are scarce." (PMID 36569944, 2022). "Studies on prolactin (PRL) and ischemic stroke are scarce, but reports on brain injury and neuroprotection have seen some advances." (PMID 36569944, 2022). "More research is needed to investigate the prolactin role in ischemic stroke." (PMID 36569944, 2022). "The enrichment results demonstrated that the “MAPK signalling pathway,” “Toll-like receptor signalling pathway,” “Prolactin signalling pathway,” “TNF signalling pathway,” “ErbB signalling pathway,” and “HIF-1 signalling pathway” were closely related to the onset and progression of ischaemic stroke." (PMID 35815278, 2022).
lymphocytic hypophysitis (5 papers, 2009 to 2023). "The sequence of anterior hormone deficiency to IgG4-RH was as follows: gonadotropin, ACTH, TSH, GH, and prolactin, which was different from lymphocytic hypophysitis that was characterized by ACTH > TSH > gonadotropin > prolactin > GH." (PMID 31929792, 2019).
metastatic disease (5 papers, 2016 to 2025). "After 20 years of follow‐up, they found an association between PRL levels <10 years before diagnosis and BC risk in post-menopausal women, especially in estrogen receptor-positive tumors and metastatic disease." (PMID 38756317, 2024). "Related study had found that the PRL and PRL receptor (PRLR) was locally expressed in prostate epithelium, and a significantly higher serum prolactin were found in patients with metastatic disease, compared with the patients without metastases." (PMID 38341429, 2024).
myocardial infarction (5 papers, 2020 to 2025). Gross necrosis of the myocardium, as a result of interruption of the blood supply to the area, as in coronary thrombosis. "In animal studies, PRL levels have been demonstrated to be elevated in myocardial infarction and associated with increased cardiovascular smooth muscle reactivity to norepinephrine and angiotensin." (PMID 41244055, 2025).
neuroendocrine tumors (5 papers, 2021 to 2024). "The present review will discuss the relationship between PRL and the pathogenesis of PRL-related neuroendocrine tumors, focusing primarily on non-aggressive lactotroph tumors, aiming to identify targets for upcoming treatment strategies." (PMID 36714572, 2022). "Histopathology was suggestive of a neuroendocrine tumor, with immunohistochemistry positive for GHRH and negative for prolactin." (PMID 39449742, 2024).
orthostatic hypotension (5 papers, 2020 to 2024). Sudden fall of the blood pressure of at least 20/10 mm Hg when a person stands up. "For example, blonanserin exhibited a reduced risk of prolactin elevation and orthostatic hypotension compared to risperidone." (PMID 38571994, 2024). "Blonanserin was associated with a lower risk of prolactin increase, weight gain, and orthostatic hypotension compared with risperidone." (PMID 31788985, 2020). "The incidences of prolactin increase, weight gain, and orthostatic hypotension were rarer for blonanserin, whereas those of akathisia and excitability were more common for blonanserin, compared with risperidone." (PMID 31788985, 2020).
ovarian dysfunction (5 papers, 2012 to 2024). The inability of the ovaries to function. "In women, low prolactin levels can inhibit formation and functioning of the corpus luteum, thereby inducing ovarian dysfunction." (PMID 39080760, 2024). "The role of dopamine also should be explored due to its inhibitory control of prolactin and known relationship with ovarian dysfunction in African elephants." (PMID 33156856, 2020). "Hormonal tests such as follicle stimulating hormone, luteinizing hormone, progesterone, thyroid function tests and prolactin level are tests done to rule out conditions that can cause ovarian dysfunction leading to possible menorrhagia." (PMID 22272207, 2012). "Endometriotic implants may also secrete prolactin (PRL) and possibly cause ovarian dysfunction." (PMID 26000006, 2015).
periodontitis (5 papers, 2023 to 2025). An acute or chronic inflammatory process that affects the tissues that surround and support the teeth. "As CAL is a key indicator of periodontitis severity, its strong association with PRL underscores the hormone’s potential involvement in PRL-associated periodontal changes." (PMID 41141060, 2025). "Pearson’s correlation analysis revealed stronger associations between PRL levels and clinical parameters in patients with periodontitis compared to healthy individuals." (PMID 41141060, 2025). "A number of biological processes are attributed to prolactin like metabolism and immune-modulation; thus, biological effects of PRL have been linked to immune-mediated inflammatory diseases like systemic lupus, multiple sclerosis, cancer, and periodontitis." (PMID 36717425, 2023). "Given that periodontitis involves inflammatory bone loss through impaired osteoblastic activity, PRL may play a contributory role in disease progression, suggesting its potential as a mechanistic link between periodontal and systemic inflammatory disorders." (PMID 41141060, 2025). "Given the limited literature on salivary PRL in periodontitis, comparisons were restricted to studies utilizing GCF samples." (PMID 41141060, 2025). "The present findings align with this paradigm, demonstrating increased levels of salivary and serum PRL in patients with periodontitis compared to healthy subjects." (PMID 41141060, 2025). "Elevated PRL levels have been observed in autoimmune and inflammatory conditions, including periodontitis." (PMID 41141060, 2025). "This supports the growing view of periodontitis as a manifestation of systemic inflammatory burden and positions PRL as a promising biomarker linking oral and systemic health." (PMID 41141060, 2025). "Elevated PRL levels in periodontitis patients correlated positively with clinical parameters, highlighting its association with disease severity." (PMID 41141060, 2025). "This study assessed salivary and serum PRL levels, along with clinical parameters, in healthy individuals and patients with Stage II-IV periodontitis, also evaluating post-treatment changes three months after SRP." (PMID 41141060, 2025). "The persistence of this correlation at three months post-treatment in periodontitis patients indicates a clear link between elevated PRL levels and periodontal disease severity." (PMID 41141060, 2025). "In the present study, mean serum PRL in the periodontitis group at baseline (13.1 ng/mL) was elevated compared with healthy individuals (6.8 ng/mL), approaching the upper limit of the normal reference range (5-20 ng/mL in females, 4-15 ng/mL in males)." (PMID 41141060, 2025). "PRL levels showed a strong baseline correlation with clinical parameters, which persisted as a weak yet significant correlation post-treatment in the periodontitis group." (PMID 41141060, 2025). "Alongside improvements in clinical parameters, the periodontitis group exhibited a notable reduction in salivary and serum PRL levels three months post-treatment." (PMID 41141060, 2025). "Local PRL levels in GCF and synovial fluid seem to be associated with the disease processes of periodontitis and RA, compared to serum levels." (PMID 39811802, 2025). "The periodontitis group exhibited considerably elevated mean salivary PRL and higher mean serum PRL values." (PMID 41141060, 2025). "Few studies have reported elevated levels of PRL in the gingival crevicular fluid (GCF) of patients with periodontitis compared to healthy controls, which have been found to decrease with periodontal therapy." (PMID 41141060, 2025). "We further confirmed these results by performing regression analysis to verify the direct causal relation between serum prolactin level and PD, BMD, and degree of periodontitis." (PMID 37875841, 2023).
periodontitis (continued). "Previously, we reported elevated levels of PRL in GCF of patients with periodontitis compared to healthy controls, and that these levels were reduced, 3 months after non-surgical periodontal therapy." (PMID 36717425, 2023). "Their subsequent study further substantiated PRL’s role as a potential inflammatory nexus between periodontitis and RA, with elevated GCF and serum PRL levels in chronic periodontitis patients, both with and without RA, which declined post-NSPT yet remained higher than the current study’s findings." (PMID 41141060, 2025). "For GCF, at baseline, RA + P group showed the highest mean prolactin levels, followed by periodontitis group that showed a significantly lower mean level while RA without periodontitis and control groups showed the lowest mean prolactin levels (P value < 0.001, effect size = 0.911)." (PMID 36717425, 2023). "Our study lacks data regarding the PRL synovial levels in periodontitis and healthy control groups." (PMID 36717425, 2023). "Thus, the present study was undertaken based on the hypothesis that PRL levels elevate in inflammatory conditions such as periodontitis, potentially serving as a valuable positive biomarker in affected individuals." (PMID 41141060, 2025). "Consequently, we hypothesized that local prolactin expression in periodontal and synovial tissues would be elevated in patients with RA and periodontitis compared to controls." (PMID 36717425, 2023). "Furthermore, given PRL’s established roles in immune modulation and bone metabolism, as well as its elevated levels in various systemic autoimmune and inflammatory disorders, its expression in periodontitis may also signal broader systemic immune dysregulation." (PMID 41141060, 2025). "This study aims to compare salivary and serum PRL levels in health and periodontitis and to evaluate the effect of non-surgical periodontal therapy on these levels." (PMID 41141060, 2025). "In this work, local PRL levels were higher in crevicular and synovial fluids of PRL in RA + P patients compared to periodontitis patients and both were greater compared to non-periodontitis RA patients and healthy controls." (PMID 36717425, 2023). "In our study, the synovial PRL in RA + P patients were higher compared to RA patients without periodontitis." (PMID 36717425, 2023). "At baseline, synovial fluid PRL levels in RA with periodontitis patients were non-significantly higher than RA patients without periodontitis." (PMID 36717425, 2023). "The primary objective of this study was to estimate and compare salivary and serum PRL levels in patients with generalized Stage II-IV periodontitis before and after non-surgical periodontal therapy, as well as in systemically healthy individuals with periodontal health." (PMID 41141060, 2025). "Therefore, the present study aims to estimate and correlate the salivary and serum PRL levels in patients diagnosed with periodontitis before and after non-surgical periodontal therapy, compared to healthy controls." (PMID 41141060, 2025). "However, no studies have assessed the levels of PRL in human saliva in the context of periodontitis." (PMID 41141060, 2025). "Non-surgical periodontal therapy in patients with periodontitis reduced PRL levels." (PMID 41141060, 2025). "Moreover, we aimed to evaluate the effect of non-surgical periodontal therapy on PRL levels in periodontitis patients with and without RA." (PMID 36717425, 2023). "Investigate the levels of PRL in GCF, synovial fluid, and serum of patients with moderate active RA, both with and without periodontitis." (PMID 39811802, 2025).
post-traumatic stress disorder (5 papers, 2023 to 2025). An anxiety disorder precipitated by an experience of intense fear or horror while exposed to a traumatic (especially life-threatening) event. "Chronically stressed individuals, such as those with post-traumatic stress disorders, mainly showed an increase in prolactin and cortisol levels." (PMID 39618560, 2024). "However, in more recent studies involving patients with post-traumatic stress disorders (PTSD) (mainly war veterans), plasma PRL levels decreased, did not change, or increased." (PMID 36833950, 2023).
premature ejaculation (5 papers, 2017 to 2024). A disorder characterized by persistent or recurrent ejaculation before or after penetration and before the person wishes it. "Luteinizing hormone, prolactin, and thyroid-stimulating hormone levels are associated with premature ejaculation which was diagnosed by premature ejaculation diagnostic tool questionnaires." (PMID 27619666, 2017).
premenstrual syndrome (5 papers, 2011 to 2023). "It is also assumed that low levels of prostaglandin E1 in women with premenstrual syndrome lead to increased sensitivity to luteal phase prolactin." (PMID 34946512, 2021). "Some women with the premenstrual syndrome have elevated prolactin levels, but in most the prolactin concentrations are normal." (PMID 21241460, 2011). "Factors including premenstrual syndrome, menses, use of birth control, and hormones (e.g., prolactin) may contribute to the female predominance of headaches." (PMID 37508629, 2023). "Furthermore, it revealed that curcumin increases prolactin levels in women with Premenstrual premenstrual Syndrome." (PMID 30234185, 2018).
primary hypogonadism (5 papers, 2020 to 2024). "Laboratory analysis revealed a hypergonadotropic hypogonadism with normal prolactin, thyroid stimulating hormone, hemoglobin, hematocrit, and kidney and liver function." (PMID 39371808, 2024). "Measurement of LH, FSH, and prolactin will help to differentiate secondary from primary hypogonadism." (PMID 38132234, 2023).